SLC6A19 (solute carrier family 6 member 19)
Diseases named in the same sentence as SLC6A19 in open-access papers (continued):
Sharing a sentence is not in itself a finding about the gene and the disease.
clear cell renal cell carcinoma (1 paper, 2025). "In the concluding segment of the article, the pivotal role of SLC6A19 in clear cell renal cell carcinoma (ccRCC) is underscored, highlighting its intriguing interplay with fatty acid metabolism." (PMID 40099255, 2025).
depression (1 paper, 2025). "Interestingly, SLC6A15 was grouped with SLC6A19 and SLC6A20 (that are interacting with ACE2) in a recent review of SLCs, and it has been linked to the hippocampus and depression." (PMID 40667466, 2025).
developmental delay (1 paper, 2023). "In wild-type mothers on the restricted diet, tryptophan levels at E9.5 were significantly lower than those in Slc6a19+/− mothers, and developmental delay was primarily observed in embryos from wild-type mothers at E9.5." (PMID 36374036, 2023).
Hyperphenylalaninemia (1 paper, 2024). "SLC6A19 inhibition was efficacious in Pahenu2 mice across a broad range of elevated basal plasma Phe levels, from classic PKU (Phe > 1,200 μM) to hyperphenylalaninemia (Phe > 360 but < 600 μM)." (PMID 39513367, 2024).
lung adenocarcinoma (1 paper, 2015). A carcinoma that arises from the lung and is characterized by the presence of malignant glandular epithelial cells. "The genes CEP72, BRD9, TRIP13, SLC9A3, SDHA, SLC6A19 and PDCD6 did not have any predictive role in lung adenocarcinoma prognosis." (PMID 26497366, 2015).
lung carcinoma (1 paper, 2025). "Knockdown of 16 of 18 (89%) CPD genes reduced viability in both cell lines —including five targets not previously implicated in lung cancer (Ephx2, Peg3, Apob, Oit1 and Slc6a19)." (PMID 40825871, 2025).
malaria (1 paper, 2024). Malaria is a serious and sometimes fatal disease caused by a parasite that commonly infects a certain type of mosquito which feeds on humans. "Consistent with our findings, a previous study in Gabonese children revealed that SLC6A19 transcripts were highly up-regulated in SMA relative to those with uncomplicated malaria." (PMID 39452740, 2024).
nephritis (1 paper, 2016). Inflammation of renal tissue. "The top 5 up-regulated genes based upon fold change between groups were: carbamoyl-phosphate synthase 1 (CPS1), carboxypeptidase O (CPO), tubulointerstitial nephritis antigen (TINAG), solute carrier family 7, member 9 (SLC7A9), and solute carrier family 6, member 19 (SLC6A19)." (PMID 27093613, 2016).
renal carcinoma (1 paper, 2021). A carcinoma arising from the epithelium of the renal parenchyma or the renal pelvis. "SLC6A19 has also been reported to be a potential biomarker that has a significantly low level of expression in patients with renal cancer." (PMID 35003220, 2021).
type 1 diabetes (1 paper, 2021). "The aim of this study was to determine if amino acid off-loading via Slc6a19 knockout would reduce the incidence or delay the onset of type 1 diabetes in NOD mice." (PMID 34677380, 2021). "In conclusion, Slc6a19 deficiency did not reduce the high incidence of insulitis and type 1 diabetes development in female NOD mice." (PMID 34677380, 2021). "We conclude that Slc6a19 deficiency does not prevent or delay the development of type 1 diabetes in female NOD mice." (PMID 34677380, 2021).
tumor (9 papers, 2021 to 2025). "By combining GWAS, EWAS, transcriptomics, metabolomics, immunophenotyping, and QTL mapping, along with MR, colocalization, transcriptome-wide association, and functional validation, we reveal SLC6A19 as a functionally relevant tumor suppressor." (PMID 40990012, 2025). "The protein encoded by SLC6A19 is highly expressed in normal kidney tissues, and located in the proximal tubules, while it is lowly expressed in tumor tissues, mainly located in the cytoplasmic and membranous regions." (PMID 38928496, 2024). "Tumors in the SLC6A19 group showed stronger SLC6A19 staining in immunohistochemistry and reduced tumor size." (PMID 40990012, 2025). "From a translation perspective, SLC6A19 correlation with favorable prognosis, immune infiltration, and tumor suppression suggests possible functions in stratifying patients for immunometabolic therapy." (PMID 40990012, 2025). "First, we conducted a comparative analysis of SLC6A19 gene expression levels between tumor and normal tissues across two distinct databases: TCGA and GSE53757." (PMID 40099255, 2025). "The dysregulation of SLC13A1 and SLC6A19 are reported to affect various type of tumor progression including ccRCC." (PMID 36090028, 2022). "The findings revealed a significant downregulation of SLC6A19 in tumor tissues." (PMID 40099255, 2025). "In vivo, SLC6A19 overexpression significantly reduced CRC xenograft tumor growth." (PMID 40990012, 2025). "In addition, pharmacological modulation or gene therapy approaches to recover SLC6A19 expression can theoretically enhance anti-tumor immune surveillance, particularly in those patients who have low SLC6A19 expression and low T-cell infiltration." (PMID 40990012, 2025). "It is speculated that MYH14 and SLC6A19 may be involved in the dynamic development of tumor stem cells through epigenetic mechanisms, as observed in our study." (PMID 38928496, 2024). "In contrast, the remaining two genes, SLC6A19 and SMIM24, have received significantly less attention in tumor-related research, with scant reports on their potential implications in oncology." (PMID 40099255, 2025). "Glutamine enters tumor cells by SLC1A5 (ASCT2), SLC38A1, SLC38A2, SLC6A14 (ATB0+), and SLC6A19 (B0AT1), which are frequently overexpressed in different malignancies." (PMID 38001865, 2023). "Secondly, SLC6A19 plays a significant role in ccRCC and presents intimately correlation with fatty acid metabolism alongside with CPT1A, which is extensively considered as a tumor suppressor of ccRCC." (PMID 40099255, 2025). "Considering the findings that MYH14 and SLC6A19 can impact TME progression through epigenetic regulation, targeting these signaling pathways may offer a dual strategy to disrupt the dynamics of tumor stem cells and epigenetic regulation within the TME, thereby delaying tumor progression." (PMID 38928496, 2024).
metabolic disorders (6 papers, 2019 to 2025). "SLC6A19 was also suggested as a potential target for the treatment of metabolic disorders, since its absence in mice was associated with decreased mTORC1 activity." (PMID 35379807, 2022). "This study highlights the potential of SLC6A19 as a knock-out or inhibition target to induce protein restriction for the treatment of metabolic disorders." (PMID 31470570, 2019). "The potential use of SLC6A19 as a target to improve metabolic disease is further exemplified by the ability of SLC6A19ko to normalize the elevated levels of phenylalanine in a mouse model of phenylketonuria." (PMID 31470570, 2019).
cancer (3 papers, 2019 to 2025). A tumor composed of atypical neoplastic, often pleomorphic cells that invade other tissues. "Pan-cancer mutation prognosis analysis showed that ACE1 and TMPRSS2 mutations were associated with better survival in cancer patients (p = 0.0273 and 1.18e−10), whereas mutated SLC6A19 was associated poor survival in cancer patients (p = 1.47e−4)." (PMID 34458283, 2021). "Various primary transporters, including B0AT1(SLC6A19), LAT1 (SLC7A5), SNAT5 (SLC38A5), and ASCT2 (SLC1A5), play significant roles in glutamine uptake by cancer cells." (PMID 40223274, 2025). "We found that TMPRSS2, SLC6A19, ATGR2, AGT, ACE2, and ACE1 had >5% CNV amplification or deletion in 33 cancers." (PMID 34458283, 2021). "However, the rest of the genes (LGI1, PCSK2, CTNND2, SLC6A19, DAO, TMEM82 and CPNE7) could be related to CRC and have been previously identified in other types of cancer." (PMID 30940089, 2019).
infection (3 papers, 2020 to 2023). The state of being infected such as from the introduction of a foreign agent such as serum, vaccine, antigenic substance or organism. "In addition, higher expression of solute carrier family genes (Slc13a1, Slc26a3, Slc2a2, Slc40a1, Slc5a1, and Slc6a19) was seen in the gastric tissue of Muc1−/− mice compared with WT at sham and 8 h infection." (PMID 32793510, 2020).
autosomal recessive inherited disorder (1 paper, 2019). "The Hartnup disorder is an autosomal recessive inherited disorder caused by mutations in SLC6A19, which encodes the neutral amino acid transporter B0AT1." (PMID 31878022, 2019).
SLC6A19 also shares sentences with these, for which no sentence is quoted: dermatitis (2 papers); alcoholic cirrhosis (1); amino acid metabolism disorders (1); androgenetic alopecia (1); biotinidase deficiency (1); cystic fibrosis (1); cystinuria (1); distal renal tubular acidosis (1); inflammation (1); kidney disease (1); maple syrup urine disease (1); Spherocytosis (1); type I citrullinemia (1).